IL10 (interleukin 10)
Diseases named in the same sentence as IL10 in open-access papers (continued):
Sharing a sentence is not in itself a finding about the gene and the disease.
vitiligo (27 papers, 2014 to 2026). Generalized well circumscribed patches of leukoderma that are generally distributed over symmetric body locations and is due to autoimmune destruction of melanocytes. "As our meta-analysis suggested impaired Tregs' suppressive capacity in vitiligo patients, we studied the expression levels of Treg-associated suppressive cytokines: IL-10 and TGF-β by calculating the standardized mean difference through meta-analysis." (PMID 36164321, 2022). "We further detected AHR related cytokines in vitiligo patients and observed declined serum IL-10 level and its association with the AHR −129C > T variant." (PMID 26370050, 2015). "AhR-mediated Treg cell differentiation and IL-10 expression may be associated with vitiligo pathogenesis, as IL-10 plays a crucial role in the development of self-tolerance." (PMID 33499346, 2021). "Studies suggest that vitiligo patients may also have an increased risk of developing celiac disease due to shared autoimmune mechanisms; indeed, celiac disease is characterized by an elevated concentration of IL-2, IL-8, and IL-10." (PMID 40430113, 2025). "Consequently, our data of genetic analysis imply that the AHR −129C > T mutation might be related to vitiligo partially by affecting IL-10 production, which further supports previous findings about AHR function in immune regulation." (PMID 26370050, 2015). "LEF administration demonstrated significant immunomodulatory capacity, reducing the serum levels of Th1-associated pro-inflammatory cytokines (IFN-γ, TNF-α, IL-2) while upregulating Th2-derived anti-inflammatory mediators (IL-4, IL-10) in vitiligo mice." (PMID 40725033, 2025). "This suggests IL-10’s significant role as a target for inflammation and immune suppression in vitiligo treatment." (PMID 39050532, 2024). "Variations were observed in the IL-10 levels in vitiligo patients at different stages of the condition, suggesting a close relationship between IL-10 and the disease’s activity and clinical staging." (PMID 39050532, 2024). "Reports have indicated a significant elevation of IL-17 and IFN-γ levels in the serum of vitiligo patients, which significantly decrease post-treatment, while IL-10 is markedly reduced in the serum, displaying immune suppression." (PMID 39050532, 2024). "For example, it has been identified that there is global hypermethylation of DNA in PBMCs, particularly in regions related to the increase of IL-10 in vitiligo patients." (PMID 35360245, 2022). "Next, to study the role of IL-10 on disease activity, we carried out disease activity-based analysis for IL-10 levels in vitiligo." (PMID 36164321, 2022). "A total of 5 studies comprised of 72 vitiligo patients (human studies) and 9 vitiligo mice (animal studies) studied the IL-10 protein levels pre- and posttreatment." (PMID 36164321, 2022). "Further, to study the expression levels of IL-10 in blood and skin of vitiligo patients, we carried subgroup analysis." (PMID 36164321, 2022). "After the initial screening, we found that a total of 6 studies comprised of 334 vitiligo patients and 341 controls assessed the IL-10 levels in vitiligo." (PMID 36164321, 2022). "Regulatory T cells (Tregs) play a key role in maintaining peripheral tolerance; however, Tregs' number, suppressive function, and associated suppressive molecules (FOXP3, IL-10, and TGF-β) are found to be reduced in vitiligo patients." (PMID 36164321, 2022). "Another study demonstrated a relationship between the production of pro- and anti-inflammatory cytokines (IL-17A, IL-10, and IL-12p70) by DCs in both stable and active patients with vitiligo." (PMID 35884944, 2022). "Therefore, AHR − 129C > T polymorphism may be related to vitiligo by altering IL-10 production." (PMID 33499346, 2021). "Recent studies demonstrated increased TNF-α concentration and decreased IL-10 production in the serum of vitiligo patients." (PMID 33499346, 2021).
vitiligo (continued). "Decreased serum concentrations of the anti-inflammatory cytokine IL-10 were observed in patients compared to controls suggesting low Th2 cytokine profile in the pathogenesis of vitiligo." (PMID 26442157, 2015). "Examination of growing feathers from vitiligo-susceptible Brown line chickens revealed anti-inflammatory immune activities which may be responsible for preventing vitiligo (IL10, CTLA4, FOXP3)." (PMID 38720888, 2024). "Furthermore, another study pointed out notable differences in the serum IL-10 levels between the general population and vitiligo patients." (PMID 39050532, 2024). "For example, data from the literature demonstrate that acute exercise induces PBMCs hypomethylation, which might upregulate IL-10 expression in vitiligo patients." (PMID 35360245, 2022). "Furthermore, the expression of key Treg-associated suppressive cytokines IL-10 and TGF-β were significantly reduced in vitiligo patients (p = 0.0005 and p = 0.01)." (PMID 36164321, 2022). "Interestingly, the levels of anti-inflammatory DC (CD11b+) and anti-inflammatory cytokine IL-10 were decreased in patients with active vitiligo, in contrast to an increased level of the pro-inflammatory cytokine IL-17A." (PMID 35884944, 2022). "Therefore, to clarify the role of Tregs in vitiligo pathogenesis, we aimed to study Tregs' frequency, suppressive capacity, and associated suppressive molecules (FOXP3, IL-10, and TGF-β) in vitiligo patients through meta-analysis approach." (PMID 36164321, 2022). "Notably, vitiligo patients have high IL-2 concentrations due to a high stimulation of T cells; and lower Tregs markers (IL-10 and forkhead box P3)." (PMID 35360245, 2022). "Interestingly, our meta-analysis suggested a significant decrease in IL-10 expression levels in vitiligo patients more specifically in blood of vitiligo patients." (PMID 36164321, 2022). "However, we found only three studies comprised of 154 vitiligo patients and 79 controls and carried out the disease activity-based analysis for IL-10 expression." (PMID 36164321, 2022). "In addition, we treated the Tregs from vitiligo patients with Hemin, an agonist of HO‐1, and found that enhanced HO‐1 expression restored the function of Tregs by up‐regulating IL‐10 expression." (PMID 29974998, 2018). "Altogether, our findings suggested that enhancing HO‐1 expression could restore the immunoregulatory function of vitiligo Tregs possibly by up‐regulating IL‐10 and LAP expression." (PMID 29974998, 2018). "This indicates that upregulation of IL-10 may be responsible for the drug response which indirectly supports the decreased levels of IL-10 in vitiligo pathogenesis observed in our study." (PMID 26442157, 2015). "Acrofacial vitiligo showed the highest IFN-γ and the least IL-10 concentrations among the variants." (PMID 26442157, 2015). "Furthermore, we evaluated Tregs' frequency, FOXP3, and IL-10 expression posttreatment in vitiligo." (PMID 36164321, 2022). "In addition, enhancing HO‐1 expression could restore the immunoregulatory function of vitiligo Tregs with up‐regulation of IL‐10 and LAP expression." (PMID 29974998, 2018). "Patients with vitiligo presented higher circulating levels of IFN-λ1 and IL-1b and ratios of IFN-λ1/IL-10 and IL-6/IL-10 (p < 0.05, p < 0.05, p < 0.001, and p < 0.01, respectively)." (PMID 42052095, 2026). "In addition, a variety of cytokines secreted by T helper cell subsets- Th1 (IFN-γ, TNF-α, IL-2) and Th2 (IL-4, IL-10, IL-13) not only exacerbate autoimmune responses but also perpetuate the vicious cycle of immune dysfunction, ultimately leading to the clinical manifestations of vitiligo." (PMID 40725033, 2025). "Concurrently, the cytokine profile shift—characterized by reduced IFN-γ, TNF-α, and IL-2, alongside elevated IL-4 and IL-10—suggests that LEF promotes an anti-inflammatory milieu, countering the Th1 axis that drives vitiligo." (PMID 40725033, 2025).
vitiligo (continued). "Highly significant changes in the expression of T cell activation-related genes IFNG, FASLG, GZMA and IL21 and anti-inflammatory genes IL10 and TGFB1 were found in growing feathers of vitiligo-expressing Smyth chickens (P < 0.0001)." (PMID 38720888, 2024). "After initial screening, 913 studies were excluded as they contained duplicate records and did not involve assessment of Tregs' frequency, Tregs' suppressive capacity, FOXP3 levels, IL-10 levels, and TGF-β levels in vitiligo." (PMID 36164321, 2022). "Overall, our meta-analysis with the previously available studies suggests the crucial role of IL-10 and TGF-β in vitiligo pathogenesis." (PMID 36164321, 2022). "In our study, we found that the weakened immunoregulatory function and proliferative ability of Tregs in vitiligo was accompanied with lower expression of some anti‐inflammatory molecules including TGF‐β, IL‐10 and CTLA‐4." (PMID 29974998, 2018). "We also investigated AHR-related cytokines and observed increased serum TNF-α concentration and diminished serum levels of IL-10 and TGF-β1 in vitiligo." (PMID 26370050, 2015). "Regulatory cytokines produced by Treg cells, such as IL-10 and TGF-β, are suggested to be related to the stability of vitiligo." (PMID 26788051, 2015). "To date, clinical reports on whether CO2 fractional laser combined with compound betamethasone injections in vitiligo treatment modulates IL-17, IFN-γ, and IL-10 inflammatory factors are scarce." (PMID 39050532, 2024). "Therefore, we performed a meta-analysis to study Treg cells' frequency, Tregs' suppressive function, FOXP3, IL-10, and TGF-β expression in vitiligo patients." (PMID 36164321, 2022). "The relative expression levels (fold change) of IFN-γ, IL-10, and IL-21, which were designated as the signature cytokines in SLV, were, however different in eyes and GF with active vitiligo (140, 15, and 30 in SL-IV eyes and 20, 37, and 38 in GF, respectively)." (PMID 35547230, 2022). "Furthermore, inflammatory factors and interleukin (IL) signaling pathway (IL4 and IL10), adaptive immune response (IFNG), and cell apoptosis (FASLG and TNF) also played critical roles in the clarification of the mechanisms of KBL on vitiligo." (PMID 31781265, 2019). "Meanwhile, there is mounting evidence that the immunological milieu of vitiligo is also characterized by cytokines connected to other Th2 cell responses, such as IL-4, IL-5, IL-10, IL-13, and IL-31, rather than just Th1 cells and related cytokines (IFN-γ, TNF-α, and IL-2)." (PMID 38695020, 2024). "Therefore, this project aims to evaluate the clinical efficacy and prognosis of CO2 fractional laser combined with compound betamethasone injections in treating vitiligo, elucidating their modulation of the inflammatory response via IL-17, IFN-γ, and IL-10, and their role in vitiligo treatment." (PMID 39050532, 2024). "Hence, we further evaluated the role of IL-10 and TGF-β in vitiligo." (PMID 36164321, 2022). "However, IL-10 and TGF-β have also been reduced in vitiligo patients." (PMID 36164321, 2022). "Furthermore, we could only find two studies assessing IL-10 and TGF-β expression levels in skin of vitiligo patients; hence, future studies with larger sample size are needed to confirm these findings." (PMID 36164321, 2022). "The ratio of IFN-γ : IL-10 serum levels may be considered as one of the promising immunological markers in nonsegmental vitiligo." (PMID 26442157, 2015). "Similarly, active vitiligo patients exhibited a positive correlation between IL-10 and IFN-γ but the stable vitiligo patients did not." (PMID 26442157, 2015). "Patients with clinical variants, with active and stable vitiligo, with and without social habits of smoking and alcohol consumption, and with and without family history of nonsegmental vitiligo also exhibited a significantly increased ratio of IFN-γ : IL-10 (p < 0.05)." (PMID 26442157, 2015).
vitiligo (continued). "Other groups have reported that IL10, IL13, IL17A, and IL21 are increased in vitiligo, though we did not observe this in our case series study." (PMID 33384688, 2020). "Nonsegmental vitiligo patients showed increased levels of IFN-γ (12.4 ± 3.2 versus 9.9 ± 4.4 pg/mL) and decreased levels of IL-10 (9.3 ± 1.7 versus 11.5 ± 5 pg/mL) compared to controls." (PMID 26442157, 2015). "Appraisal of proinflammatory and anti-inflammatory cytokines in relation to active and stable vitiligo revealed significantly elevated amounts of IFN-γ and IFN-γ : IL-10 ratio and no variation in the serum concentrations of IL-10." (PMID 26442157, 2015). "Finally, we found that expression levels of IL-6 (0.27-fold) and IL-17 (0.30-fold), but not IL-10 or IFN-γ, were also decreased in T cells from patients with vitiligo (n = 6) compared with the controls (n = 6), after the transfection of plasmid encoding LOC100506314." (PMID 37731844, 2023).
dementia (26 papers, 2011 to 2025). Loss of intellectual abilities interfering with an individual's social and occupational functions. "In contrast, B cells isolated from PD patients at a greater risk of dementia exhibited increased levels of IL-6 and IL-10." (PMID 38020762, 2023). "Previously, we reported the possible association of the IL10 (−1,082 and −819) polymorphisms in conferring dementia in a Mexica population." (PMID 36389080, 2022). "Whereas an increased IL-5/IL-10 ratio has been reported in patients with atopic asthma, atopy itself is associated with a modest rise in the risk of dementia, in support of an inflammatory component in the etiology of neurodegenerative dementia." (PMID 24655894, 2014). "However, IL10 has been reported at higher levels in patients with dementia compared to healthy controls and brain IL-10 levels are increased in neurological diseases, including AD." (PMID 34802467, 2021). "However, patients with dementia are reported to have higher mean levels of IL-10, and an increase in brain IL-10 has been reported in neurological disease, including AD." (PMID 21569380, 2011). "Longitudinal population studies are needed to understand the role of body fat indices and IL-10 in pre-frail older adults with MCR and trajectory to dementia." (PMID 37371414, 2023). "Specifically, we found significantly higher levels of IL-10, IL-1beta, IL-4 and IL-2 in both MCI-LB and MCI-AD compared with dementia and control subjects." (PMID 29248892, 2018). "Furthermore, we analyzed the association between IgG N-glycome and markers of inflammation including anti-inflammatory (IL-4 and IL-10) as well as proinflammatory factors (CRP, TNF-α, IFN-γ, IL-1β, and IL-6), contributing to explain the role of IgG glycosylation on dementia." (PMID 33542243, 2021). "Meanwhile, we investigate the associations between IgG N-glycan profiles and inflammation factors including anti-inflammatory (IL-4 and IL-10) and proinflammatory factors [IL-1β, IL-6, CRP, TNF-α, and interferon-gamma (IFN-γ)], which may further explain the role of IgG glycosylation in dementia." (PMID 33542243, 2021). "Interestingly, IL-10 has been found to be increased in brain samples derived from humans with intermediate probability of AD in the absence of dementia, designated as resilient." (PMID 31396076, 2019). "We found IL-10 levels to differ between clinical AD stages but not between NC– and AD dementia." (PMID 30253800, 2018).
diffuse large B-cell lymphoma (26 papers, 2012 to 2025). "High amounts of IL-10 in sera of diffuse large B-cell lymphoma (DLBCL), CLL, glioma, and cutaneous T cell lymphoma patients are considered as a marker of unfavorable prognosis." (PMID 39281678, 2024). "Tumor cell‐derived IL‐10 can promote autonomous cell growth and immune escape in diffuse large B cell lymphomas, and neutralizing IL‐10 signaling can reduce tumor growth." (PMID 37547175, 2023). "Increases in IL-10 were observed in a patient with diffuse large B-cell lymphoma who experienced a fatal IRR after treatment with rituximab." (PMID 34018029, 2021). "Constitutive STAT3 activation by autocrine production of IL-6 and IL-10 is found in activated B cell-like (ABC) diffused large B cell lymphoma cell lines (DLBCL)." (PMID 31293595, 2019). "The BCR is also able to induce the IL-10/STAT3 signaling with increased expression of PD-L1 in diffuse large B-cell lymphoma." (PMID 31382969, 2019). "Among them, IL-10 -3575 A > T and TNF-α-308 G > A SNPs were reported to be associated with NHL, especially in diffuse large B-cell lymphoma (DLBCL) by several different groups." (PMID 26108796, 2015). "Beguelin and associates reported that IL-10 promotes tumor cell proliferation and survival by STAT3 signal pathway, and blocking of IL-10 receptor was suggested as a novel therapeutic target in diffused large B-cell lymphoma." (PMID 26528857, 2015). "Diffuse large B-cell lymphoma (DLBCL) cells also produce IL-10 to induce PD-L1 expression on DLBCL cells through the activation of the JAK2/STAT3 pathway." (PMID 34063096, 2021). "Human inherited IL-10 receptor deficiency was also associated with a high risk of non-EBV–related diffuse large B-cell lymphoma suggesting that IL-10 signaling may be involved in the immune control of germinal center B-cell lymphoma." (PMID 31799221, 2019). "Moreover, the role of IL-10 in Hodgkin’s lymphoma, diffuse large B-cell lymphoma (DLBCL) and Burkitt’s lymphoma had also been extensively studied." (PMID 33154947, 2020). "Diffuse large B-cell lymphoma (DLBCL), the most frequent malignant lymphoma in adults, is characterized by constitutive NF-κB activation and consequently by a constitutive production of interleukin-6 (IL-6) and IL-10." (PMID 38539832, 2024). "Doxorubicin-induced senescence promoted the recruitment of Treg cells and myeloid-derived suppressor cells to mediate apoptotic resistance in diffuse large B-cell lymphoma (DLBCL) via pro-inflammatory cytokines, such as IL-2, IL-6, IL-8, IL-10, IL-35, TGFβ, and VEGF." (PMID 36834846, 2023). "Interestingly similar observations were made in diffuse large B-cell lymphoma (DLBCL) showing that STAT3 and NFAT2 interaction induced an immunoregulatory phenotype in malignant B cells with the upregulation of IL-10 and programmed Death-Ligand 1 (PDL1)." (PMID 35359922, 2022).